MBIP (MAP3K12 binding inhibitory protein 1)
Description:
Functions as part of the ATAC complex, a complex with histone acetyltransferase activity on histones H3 and H4. Inhibits the MAP3K12 activity to induce the activation of the JNK/SAPK pathway. Together with MOCS2B, inhibits the activity of stress kinase EIF2AK2/PKR; this may lead to effects such as suppression of JNK activation and subsequent stress-responsive transcription, or suppression of eIF2a phosphorylation to favor translation.
Tractability: PROTAC: UniProt records ubiquitination sites on it; ubiquitination databases record sites on it.
Gene: Protein-coding gene on chromosome 14 (36,298,555 to 36,320,671, reverse strand). Ensembl gene ENSG00000151332.
Subcellular location: Nucleus; Cytoplasm
Subcellular location (Human Protein Atlas): Cytosol; Nucleoli; Nucleoplasm
Pathways (Reactome):
Chromatin organization: HATs acetylate histones
Gene expression (Transcription): Formation of WDR5-containing histone-modifying complexes
Gene Ontology:
Molecular function: identical protein binding; protein binding; protein kinase inhibitor activity
Biological process: negative regulation of transcription by RNA polymerase II; positive regulation of gene expression; positive regulation of JNK cascade; regulation of cell cycle; regulation of cell division; regulation of DNA-templated transcription; regulation of transcription by RNA polymerase II; regulation of tubulin deacetylation; regulation of embryonic development
Cellular component: ATAC complex; cytoplasm; cytosol; nucleolus; nucleoplasm; nucleus; mitotic spindle
Genetic constraint (gnomAD): Loss-of-function variants: 22 observed, 29.44 expected, observed/expected ratio (o/e) 0.75, 90% interval 0.53 to 1.07. The upper end of that interval is the gene's LOEUF score, 1.07, which puts it in group 4 of 6, group 1 being the genes least tolerant of losing a copy. Missense variants: 300 observed, 327.92 expected, observed/expected ratio (o/e) 0.91, 90% interval 0.83 to 1.01. Synonymous variants: 114 observed, 119.84 expected, observed/expected ratio (o/e) 0.95, 90% interval 0.82 to 1.11.
Homologues: Orthologues: chimpanzee MBIP (99% identical), macaque MBIP (97% identical), pig MBIP (90% identical), rabbit MBIP (90% identical), dog MBIP (88% identical), guinea pig MBIP (88% identical), rat Mbip (84% identical), mouse Mbip (82% identical), tropical clawed frog mbip (47% identical), zebrafish mbip (47% identical), Drosophila melanogaster CG12016 (8% identical). Paralogues in human: MOCS2 (11% identical), NMRK2 (10% identical), NMRK1 (9% identical).
Diseases named in the same sentence as MBIP in open-access papers:
MBIP is named in the same sentence as 12 diseases in open-access papers, as found by Europe PMC text mining. Sharing a sentence is not in itself a finding about the gene and the disease. The quoted sentences say what the papers report.
breast carcinoma (3 papers, 2020 to 2022). "Remarkably, three enhanced looping genes in resistant breast cancer cells, ACP1, HECTD1, and MBIP, identified and validated by HiSIF and 3C/RT-qPCR, have been previously shown to be involved in breast cancer cell transformation and progression." (PMID 32787954, 2020). "MBIP has also been found to contribute to the development of breast cancer in a genome-wide pathway analysis." (PMID 32787954, 2020).
thyroid cancer (2 papers, 2013 to 2024). "On the other hand, some of the genes determining variation in TSH levels are also known (oncogenic) genes in thyroid cancer such as MBIP, IGFBP5 and B4GALNT365–67." (PMID 38291025, 2024).
Alzheimer disease (1 paper, 2024). A progressive, neurodegenerative disease characterized by loss of function and death of nerve cells in several areas of the brain leading to loss of cognitive function such as memory and language. "Moreover, the CC2D2B, PDXDC2P, and MBIP genes exhibited strong negative associations, which are also linked to Alzheimer's disease (AD), thus suggesting that healthy diets may help maintain cognition during aging." (PMID 39351424, 2024).
Obesity (1 paper, 2023). Accumulation of substantial excess body fat. "We also identified CpGs and genes with links to obesity (NTRK2, PSTPIP2, MBIP) and glucose and fat metabolism (IRS1)." (PMID 37649101, 2023).
thyroid (1 paper, 2021). "The gene product of MBIP regulates the JNK pathway which is involved in intracellular signaling of thyroid and other human cancers." (PMID 33903625, 2021).
MBIP also shares sentences with these, for which no sentence is quoted: cancer (2 papers); endocrine disorders (1); hypothyroidism (1); lung carcinoma (1); papillary thyroid carcinoma (1); thyroid tumour (1); tumour (1).